RNU6-1073P (RNA, U6 small nuclear 1073, pseudogene)
Gene: Small nuclear RNA gene on chromosome 9 (1,001,858 to 1,001,963, reverse strand). Ensembl gene ENSG00000252991.
Homologues: Orthologues: chimpanzee U6 (98% identical), guinea pig U6 (79% identical), mouse Gm26327 (76% identical). Paralogues in human: RNU6-1243P (83% identical), RNU6-1060P (82% identical), RNU6-116P (82% identical), RNU6-22P (82% identical), RNU6-308P (82% identical), RNU6-884P (82% identical), RNU6-1020P (81% identical), RNU6-11P (81% identical), RNU6-1309P (81% identical), RNU6-17P (81% identical), RNU6-183P (81% identical), RNU6-18P (81% identical), and 1287 more.